KL (klotho)
Diseases named in the same sentence as KL in open-access papers (continued):
Sharing a sentence is not in itself a finding about the gene and the disease.
renal fibrosis (continued). "Furthermore, miR-34a exerts its pro-fibrotic effects by downregulating the expression of the negative regulator of fibrosis, Klotho, through direct binding to its 3’UTR, thereby fostering renal fibrosis." (PMID 39325739, 2024). "More recently, the downregulation of Klotho in mice has been related to an increase in ROS production, which activates the Nrf2/ARE signaling pathway and promotes the expression of fibrosis-related genes, thus accelerating renal fibrosis." (PMID 36829798, 2023). "In this regard, the klotho/Wnt/β-catenin pathway is known to be involved in the renal fibrosis of aged kidneys and of CKD, because klotho expression is reduced in aged or impaired kidneys and because the activation of Wnt signaling is responsible for the aging phenotype in klotho mice." (PMID 35016606, 2022). "Administration of s-Klotho protein inhibits TGF-β signaling and protects against renal fibrosis." (PMID 35903083, 2022). "KP1 was comparable with Klotho in inhibiting TGF-β signaling and renal fibrosis after UUO." (PMID 35064106, 2022). "FGF23 preferentially stimulates left ventricular hypertrophy and inhibition of Klotho augments myocardial fibrosis, but whether FGF23 would promote renal fibrosis remains unclear." (PMID 33460402, 2021). "In addition, the upregulation of Klotho prevents Wnt activation, thereby inhibiting the deposition of ECM and reducing the transcription of cytokines, ultimately improving renal fibrosis." (PMID 34483931, 2021). "Klotho as a regulator of calcium homeostasis inhibits transient receptor potential channel 6 (TRPC6)-mediated Ca2+ influx in cultured mouse podocytes and ameliorates albuminuria and renal fibrosis 41,42." (PMID 33162804, 2020). "Additionally, administration of recombinant soluble Klotho showed comparable effects as it reduced renal fibrosis in AKI and UUO models, suggesting these effects are primarily driven by soluble Klotho." (PMID 33585584, 2020). "In ischemic AKI model, Klotho decreases at acute phase, and together with high phosphate challenge promotes AKI to CKD progression, while Klotho improves AKI recovery and attenuates renal fibrosis by maintaining normal autophagy." (PMID 33362554, 2020). "In contrast, soluble klotho protein directly binds to the TGF-β type-II receptor and inhibits TGF-β1 binding to cell surface receptors, thereby inhibiting TGF-β1 signalling in mice with UUO-induced renal fibrosis." (PMID 30348110, 2018). "Previous report showed that Nrf2 activation can restore the expression of klotho, an anti-aging protein, suppressing TGF-β1 induced EMT in renal fibrosis, and then attenuate oxidative stress and inflammation in CKD.OA is a well-known activator of the transcription factor Nrf2." (PMID 29973206, 2018). "Notably, investigations into the role of klotho in mediating exercise-induced improvements in renal fibrosis remain conspicuously absent from the literature." (PMID 39325739, 2024). "Furthermore, Klotho exerts its influence on renal fibrosis via downstream signaling pathways, including but not limited to the transforming growth factor-β1 (TGF-β1)/Smad3 and wnt/β-catenin pathways." (PMID 39325739, 2024). "Klotho protein could compete with TGF-β1 for binding, resulting in reduced binding of TGF-β1 to cell surface receptors, which in turn inhibited the TGF-β1 downstream signaling pathway and improved renal fibrosis." (PMID 39325739, 2024). "In contrast, in UUO models, blocking DOT1L with EPZ5676 alleviates renal fibrosis by inhibiting multiple fibrosis pathways (including Smad3, EGFR, PDGFR and NF-κB pathway), up-regulating the expressions of renal protective factors such as PTEN, Klotho and Smad7,2." (PMID 35559246, 2022).
renal fibrosis (continued). "Furthermore, a decrease of soluble Klotho in CKD was reported to be an important cause of uremic cardiomyopathy or to inhibit renal fibrosis in an FGF23-independent manner, while FGF23 can induce myocardial hypertrophy independent of Klotho." (PMID 33460402, 2021). "However, serum creatinine, renal fibrosis, and Klotho were not significantly different in the fish oil-treated group." (PMID 30208590, 2018). "Soluble Klotho can suppress renal fibrosis and preserve renal function in UUO model of renal injury, therefore it could be considered as a novel therapeutic agent in renal fibrosis." (PMID 24693499, 2013). "Our findings indicate that FGF23 promotes renal fibrosis may not depend on Klotho." (PMID 33460402, 2021). "Therefore, we hypothesized that FGF23 may also play a role in renal fibrosis, either with Klotho or independent of Klotho." (PMID 33460402, 2021). "Therefore, our results demonstrated that Klotho inhibits the EndoMT process, which may be beneficial to delay renal fibrosis and this anti-fibrotic effect was possibly through the blockade of TGF-β1 signaling, thus indicating that Klotho protects against renal fibrosis." (PMID 31024315, 2019). "It is also interesting to note that in mice with renal fibrosis induced by UUO, the inhibition of Klotho increased TGF-β1 expression; Klotho expression, however, not only attenuated pathological outcomes marked by inflammation, but also induced the decrease of fibrosis markers." (PMID 35056905, 2021).
diabetes (127 papers, 2013 to 2026). "A schematic overview of Klotho gene polymorphisms and their clinical implications was developed to explore the genetic contribution of Klotho variants to diabetes susceptibility and complications." (PMID 41438297, 2025). "Studies showed that Klotho deficiency in diabetes was associated with podocyte apoptosis, podocyte injury, and proteinuria." (PMID 39859443, 2025). "For example, BMI is a commonly utilized obesity metric that correlates with body composition, while chronic conditions like diabetes and hypertension can impact metabolic pathways associated with Klotho expression." (PMID 40678338, 2025). "In recent years, with the continuous development of genomics and individualized medicine, researchers have gradually focused on the role of Klotho gene polymorphism in diabetes and its complications." (PMID 41438297, 2025). "Their combined activity helps maintain β-cell integrity, modulate insulin dynamics, and protect the pancreas from metabolic injury, providing mechanistic insight into why Klotho deficiency contributes to impaired insulin secretion and diabetes progression." (PMID 41438297, 2025). "Second: A growing number of clinical studies have shown that serum or urine Klotho levels are closely related to the risk and progression of diabetes and its complications." (PMID 41438297, 2025). "In individuals with obesity and diabetes, lower serum Klotho levels were associated with compromised whole‐body energy metabolism." (PMID 40678338, 2025). "Research indicates that Klotho-deficient mice with STZ-induced diabetes exhibit poor kidney function." (PMID 40362229, 2025). "Previous studies have associated serum Klotho levels with renal insufficiency, hypertension, diabetes, CHD, and cancer." (PMID 39723163, 2024). "Lower levels of Klotho were also found in adults with a higher risk of cardiovascular disease, such as obesity, smoking, diabetes, and higher levels of total cholesterol and triglycerides." (PMID 38672115, 2024). "In humans, lower Klotho levels are associated with increased fasting glucose, insulin resistance, increased glycated hemoglobin, and diabetes prevalence." (PMID 38501099, 2024). "Klotho concentration, as an aging‐related molecule, has been reported to be significantly associated with diabetes all‐cause mortality, cancer mortality and CVD." (PMID 39114957, 2024). "Altogether, our results demonstrate that the protective effect of AS-IV in upregulating klotho expression in diabetes-induced podocyte injury is associated with the inhibition of NLRP3-mediated pyroptosis via the NF-κB signaling pathway." (PMID 37261217, 2023). "The antioxidative effects of Klotho have been also determined in diabetic kidney disease, a serious complication of diabetes and the leading cause of end-stage kidney disease globally." (PMID 36829798, 2023). "Serum manganese levels were positively associated to serum klotho levels after they were stratified based on variates such as age, gender, race, hypertension, and diabetes (P for interaction >0.05)." (PMID 36970731, 2023). "We derived that the association between the odds of developing anemia with diabetes and Klotho was stronger (P <0.05 for the interaction)." (PMID 36797683, 2023). "Multivariate logistic regression and restricted cubic spline (RCS) regression were conducted to explore the association between serum Klotho levels and the prevalence of diabetes." (PMID 36440221, 2022). "Of these, only miR-192 is negatively correlated with circulating levels of KL in children with prolonged duration of diabetes, which we expect is associated with an increased risk for diabetic complications." (PMID 35992154, 2022). "Considering the strong association of diabetes with aging and the anti-aging property of Klotho, a lower prevalence of diabetes appears to be more reasonable as serum Klotho concentrations increase." (PMID 36440221, 2022).
diabetes (continued). "When log2-transformed serum Klotho level ≤ median, the decreasing prevalence of diabetes was associated with increasing Klotho level." (PMID 36440221, 2022). "In participants> 57 years old, obese, or with diabetes, the association between eGFR and Klotho was detected with a higher effect size." (PMID 36276390, 2022). "Serum levels of miR-192 are negatively associated with circulating KL levels in children with prolonged duration of diabetes, suggesting a regulatory role of miR-192 in the expression of soluble KL." (PMID 35992154, 2022). "Klotho has also been reported to have a role in regulating the diabetes-associated signaling of intracellular insulin/insulin-like growth factor 1 (IGF 1)." (PMID 36140700, 2022). "In a rat model with multiple cardiovascular risk factors, including hypertension, diabetes, obesity, and hyperlipidemia, in vivo Klotho gene delivery can ameliorate vascular endothelial dysfunction." (PMID 35053218, 2022). "Conversely, when log2-transformed serum Klotho levels were higher than the median value, increasing Klotho levels were associated with a higher prevalence of diabetes." (PMID 36440221, 2022). "In this regard, further studies are needed to clarify the exact causal relationship between diabetes and Klotho levels." (PMID 36440221, 2022). "Our study is the first to detect the association of Klotho with diabetes in a large, unselected population." (PMID 36440221, 2022). "Few studies to date investigated s-Klotho levels in patients with diabetes and little information is available on its association with chronic micro- and macro-vascular complications as well as with glycemic control." (PMID 35286490, 2022). "Association between serum Klotho levels and diabetes mellitus in the database from NHANES 2007-2016." (PMID 36440221, 2022). "The early vascular aging which is seen in hypertension, diabetes and renal failure, is associated with decreased renal expression and decreased levels of Klotho in serum and urine." (PMID 34670596, 2021). "The aim of this study was to evaluate if Klotho protein concentration in children with type 1 diabetes and its correlation with classical risk factors of chronic complications of diabetes: dysglycemia and endothelial dysfunction." (PMID 34603200, 2021). "In a mice model it was demonstrated that Klotho deficiency aggravated diabetes-induced podocyte injury and proteinuria, while its overexpression partially ameliorated such complication." (PMID 34603200, 2021). "Both LC3 and Klotho are underexpressed in pancreatic islet β-cells of diabetic patients and in a mouse model of diabetes (db/db mice), and such downregulation of Klotho is associated with a decrease in insulin storage in pancreatic β-cells." (PMID 34737707, 2021). "Diabetes also induced increase of kidney weight and ratio of kidney weight to body weight and Klotho deficiency induced greater increase of those." (PMID 33162804, 2020). "Reduced blood klotho concentration is also associated with increased albuminuria, especially in patients with diabetes." (PMID 29590173, 2018). "Our previous study reported that klotho deficiency was also associated with albuminuria, particularly in patients with diabetes." (PMID 29590173, 2018). "Our results indicate that the variant G‐395A, located in the promoter region, influences Klotho gene vascular expression and is associated with the incidence of diabetes." (PMID 26538295, 2016). "Considering crucial roles oxidative stress plays in aging and age-associated diseases such as cancer, diabetes and stroke, comprehensive mechanistic understanding of Klotho’s activity in pathways that regulate oxidative stress should be a pressing issue." (PMID 26452228, 2015). "Enhanced eryptosis, suicidal erythrocyte death, is observed in diabetes and eryptosis is further enhanced in klotho-deficient mice." (PMID 25084095, 2014). "Studies demonstrate that low Klotho concentrations may indicate renal dysfunction associated with diabetes." (PMID 41155157, 2025).
diabetes (continued). "Therefore, decreased urinary excretion of Klotho can be considered as a possible risk factor for albuminuric CKD in diabetes." (PMID 38540101, 2024). "Therefore, the association of Klotho with vascular disorders in patients with diabetes appears to differ depending on the specific disease conditions, particularly renal health status." (PMID 37686263, 2023). "Furthermore, stratified analyses yielded a stronger association between reduced anemia and high levels of Klotho in men and those with diabetes (P< 0.05 for interaction)." (PMID 36797683, 2023). "Finally, given that changes in Klotho concentrations were not considered in the NHANES study, our results can only reflect the positive association between Klotho and diabetes during the initial phase of the study." (PMID 36440221, 2022). "Therefore, the significance of long-term Klotho concentrations in predicting the risk of diabetes remains unelucidated." (PMID 36440221, 2022). "Participants who were male, younger than 60 years old, had a history of hypertension and a higher level of eGFR (≥ 90 ml/min/1.73 m2) were inclined to have a higher risk of diabetes in the highest quartile (Q4) of Klotho than those in Q1 (all P for trend < 0.05)." (PMID 36440221, 2022). "Therefore, we aimed to investigate the association between serum levels of Klotho and the prevalence of diabetes from the National Health and Nutrition Examination Survey (NHANES) 2007 to 2016 data." (PMID 36440221, 2022). "This may be correlated with the previously reported aggravation of diabetes-induced oxidative stress, inflammation, podocyte injury, and apoptosis, resulting in proteinuria, that are caused by Klotho deficiency." (PMID 34360633, 2021). "However, klotho concentration, blood pressure, and arterial stiffness were highly dependent on age and other cardiovascular risk factors, such as diabetes mellitus, cigarette smoking, CKD, and metabolic syndrome." (PMID 33504927, 2021). "Here, we investigated the function of Klotho deficiency on MtD of diabetes-induced podocytes." (PMID 33162804, 2020). "Secreted Klotho has been associated with cardiovascular events and mortality in the general population and various sub-populations (i.e. the elderly or patients with diabetes), however relevant studies in CKD patients are inconsistent." (PMID 31185930, 2019). "Dysregulation of the FGF23-Klotho axis contributes to disturbed mineral homeostasis and as such might increase cardiovascular risk in diabetes." (PMID 23945089, 2013). "Moreover, obesity and poor metabolically healthy are often linked to conditions such as such as insulin resistance and diabetes, which may impact Klotho levels by altering the endocrine environment and metabolic pathways." (PMID 40060377, 2025). "In recent years, with the increasing research on Klotho in aging and metabolic diseases, clinical epidemiological evidence has gradually focused on the correlation between serum or urine soluble Klotho (sKlotho) levels and the risk of diabetes and metabolic control." (PMID 41438297, 2025). "In addition, Klotho gene polymorphisms (such as G-395A, C1818T, KL-VS) are potentially associated with the susceptibility to diabetes and its complications, suggesting that individualized risk assessment and intervention can be carried out in the future in combination with genetic background." (PMID 41438297, 2025). "Moreover, in patients with type 2 diabetes mellitus, a condition often associated with obesity, lower serum klotho levels were observed in those with moderate cognitive impairment, further linking metabolic health and klotho expression." (PMID 40076542, 2025). "However, infusion of soluble Klotho may reverse such conditions, thus indicating the pathophysiological importance of Klotho in the underlying mechanism of both type 1 diabetes mellitus and GABA-induced improvement." (PMID 38213484, 2024).